DEFB109C (defensin beta 109C (gene/pseudogene))
Description:
Has antibacterial activity.
Synonyms: DEFB109
Tractability: Antibody: UniProt places it where antibodies can reach, with medium confidence; UniProt predicts a signal peptide or a membrane-spanning region.
Gene: Protein-coding gene on chromosome 8 (7,990,270 to 7,997,645, reverse strand). Ensembl gene ENSG00000205989.
Subcellular location: Secreted
Homologues: Orthologues: dog DEFB109B (72% identical), rat Defb42 (64% identical), mouse Defb48 (60% identical). Paralogues in human: DEFB109B (100% identical), DEFB109D (91% identical), DEFB130A (39% identical), DEFB130B (39% identical), DEFB4A (21% identical), DEFB4B (21% identical).